CHI3L1 (chitinase 3 like 1)
Diseases named in the same sentence as CHI3L1 in open-access papers (continued):
Sharing a sentence is not in itself a finding about the gene and the disease.
movement disorder (1 paper, 2025). Neurological conditions resulting in abnormal voluntary or involuntary movement, which may impact the speed, fluency, quality and ease of movement. "This study examines chitinase‐3‐like 1 protein (CHI3L1) as a diagnostic tool for patients with cognitive and movement disorders." (PMID 40495463, 2025).
reproductive diseases (1 paper, 2024). "Many studies have shown that Chi3l1 serves as a useful biomarker for a series of reproductive diseases." (PMID 39769202, 2024).
CHI3L1 also shares sentences with these, for which no sentence is quoted: idiopathic pulmonary fibrosis (15 papers); Parkinson disease (15); type 1 diabetes (12); kidney disease (11); Airway obstruction (10); dementia with Lewy bodies (9); vascular dementia (9); cystic fibrosis (8); systemic sclerosis (8); acute myocardial infarction (7); carotid atherosclerosis (7); systemic lupus erythematosus (7); Atrophy (6); hyperlipidemia (6); respiratory diseases (6); synucleinopathies (6); viral pneumonia (6); alcoholic liver diseases (5); Allergy (5); Autoimmunity (5); essential hypertension (5); joint disease (5); myelofibrosis (5); non-alcoholic fatty liver disease (5); psoriatic arthritis (5); renal dysfunction (5); ulcerative colitis (5); adenoma (4); atopic asthma (4); cerebrovascular disease (4).
A further 260 diseases each share a sentence with CHI3L1 in 4 papers or fewer.